CCL5 (C-C motif chemokine ligand 5)
Diseases named in the same sentence as CCL5 in open-access papers (continued):
Sharing a sentence is not in itself a finding about the gene and the disease.
ovarian carcinoma (80 papers, 2010 to 2025). A malignant neoplasm originating from the surface ovarian epithelium. "Intriguingly, we identified the chemotactic factors CCL2 and CCL5 in the CM of macrophages and found that they were associated with the adhesion of ovarian cancer cells to mesothelial cells." (PMID 36766725, 2023). "Increased levels of the chemokines CXCL9, CXCL10, CXCL11, and CCL5 are all associated with an immune-reactive ovarian cancer microenvironment and improved patient prognosis." (PMID 35131874, 2022). "Malignant cells isolated from the ascites of patients with ovarian cancer were enriched in NK clusters presenting high levels of the CCL5 gene, whose expression was deficient in ovarian cancer cells that expressed high levels of SDC4." (PMID 34680190, 2021). "It has been also demonstrated that cancer-associated fibroblast (CAF)-derived CCL5 has important roles for cisplatin resistance in ovarian cancer, and CD4+ cell-derived CCL5 is involved in the growth and immune escape of gastric carcinoma cells." (PMID 33671956, 2021). "In turn, CAF-derived p38-regulated cytokines and chemokines, such as IL-6, CXCL10, and CCL5, mobilize glycogen that is associated with fueling glycolysis in cancer cells, increasing proliferation, invasion, and metastasis of ovarian cancer." (PMID 30568223, 2019). "We found that neutralization of CCL5 significantly reduced NF-κB activity caused by CSLCs co-culture, in both A2780-derived (p<0.05) and human ovarian cancer tissue-derived NCSLCs (p<0.05)." (PMID 25788271, 2015). "Evidence supporting an association between CCL5 and ovarian carcinoma progression was also provided by a study analyzing chemokine levels in plasma of patients at different stages of disease." (PMID 24523569, 2014). "Functionally, ovarian tumor cells activate fibroblasts or induce cancer-associated fibroblasts-phenotype to promote ovarian cancer progression and reduce overall survival by secreting lysophosphatidic acid, interleukin-1β (IL-1β), and C-C motif chemokine ligand 5 (CCL5)." (PMID 36119108, 2022). "The enhanced invasiveness is mediated through NF-κB activation along with elevated MMP-9 secretion, suggesting that the autocrine activation of CCR1 and CCR3 by CCL5 represents one of the major mechanisms underlying the metastatic property of ovarian cancer cells." (PMID 24523569, 2014). "Platinum-based therapy-resistant ovarian cancer patients have a higher expression of CCL5 compared to chemo-sensitive patients." (PMID 40076892, 2025). "Activated platelets release molecules and growth factors such as EGF, PDGF, TGF-β, IGF and CCL5 to promote the expansion of ovarian cancer cells, protecting tumor cells from chemotherapy." (PMID 39707577, 2024). "SNAI2/Slug, and SNAI1/Snail have been reported to be upregulated by treatment with TGF-β and BMP as well as by treating ovarian cancer cells with IL-17, chemokine CCL5, and CCL19/CXCR7." (PMID 36766756, 2023). "CAFs provide ovarian cancer cells resistance to cisplatin by secreting cisplatin-induced chemokine (C-C motif) ligand 5 (CCL5), which augments the phosphorylation of STAT3 and Akt in cancer cells." (PMID 37065872, 2023). "Macrophages produced higher amounts of CCL2 and CCL5 compared to Met5A, ovarian cancer, and IOSE80PC cells." (PMID 36766725, 2023). "Cisplatin treatment induced CCL5 secretion in ovarian cancer tissue and cisplatin-resistant patients had high CCL5 levels." (PMID 38032111, 2023). "Consistently, CCL5-overexpressing murine ovarian cancer and hepatocellular carcinoma showed reduced tumor growth by recruiting CCR5-expressing CD8+ T cells." (PMID 34885241, 2021). "In preclinical studies using mouse models of ovarian cancer, osteosarcoma, prostate and breast cancer, CCL5 antagonists inhibited cancer cell migration and invasion." (PMID 34683963, 2021).
ovarian carcinoma (continued). "In particular, the increased expression of CCL5 has been shown to correlate with better clinical outcomes in several cancers including thyroid cancer, lung cancer, ovarian cancer, and melanoma." (PMID 34885241, 2021). "The main finding of this study was the correlation of CCL5 gene expression in NKs with ovarian cancer progression and poor prognosis." (PMID 34680190, 2021). "In ovarian cancer, the increased miR‐155 expression can transform fibroblasts into CAFs, thereby increasing the production of CCL5 and promoting the growth of tumour cells." (PMID 33943003, 2021). "Anti-CCL5 blocking antibody or CCL5-shRNA knockdown in ovarian cancer stem-like cells decreased MMP-9 mRNA expression, and consequently reduced invasiveness." (PMID 34683963, 2021). "CCL5 secreted by CD133+ ovarian carcinoma stem-like cells increases the invasive and metastatic properties of non-ovarian carcinoma stem-like cells (CD133–) and induces an EMT-like process." (PMID 32630699, 2020). "In accordance, anti-CCL5 antibody decreased tumor growth and the invasive property induced by miR-CAF co-injected in an orthotopic ovarian cancer mouse model, confirming CCL5 is a tumor-promoting factor." (PMID 32630699, 2020). "In the case of CAFs, stimulation with cisplatin increases CCL5 secretion contributing to chemoresistance in ovarian cancer." (PMID 32499779, 2020). "Blocking CCL5 or the corresponding receptors decreased the invasive capability of ovarian carcinoma cells, suggesting that the CCL5/CCR5 axis is important to the metastatic property of ovarian carcinoma stem-like cells." (PMID 32630699, 2020). "Consistently, in ovarian carcinoma tissues, tumor cells and stromal cells increased CCL5 after cisplatin treatment, and cisplatin-resistant patients had high CCL5 levels that correlated with cancer stage." (PMID 32630699, 2020). "CD133(+) ovarian cancer stem-like cells promote the metastasis of CD133(−) cancer cell metastasis via CCL5-induced EMT." (PMID 33425911, 2020). "Co-injection of tumor cells and CAFs increased CCL5 expression, cisplatin resistance and ovarian carcinoma cell proliferation in tumor xenografts." (PMID 32630699, 2020). "Serum CCL5 levels are higher in women with ovarian cancer than in women with benign ovarian cysts, correlating with the extent of disease." (PMID 32630699, 2020). "In CD133+ ovarian carcinoma stem-like cells selected from ovarian carcinoma cell lines and primary tissues, CCL5 and its receptors CCR5, CCR1, and CCR3, were up-regulated." (PMID 32630699, 2020). "MSCs protect ovarian carcinoma cells from chemotherapy by secreting CCL5 and CCL2, which induce the release of IL-6 by ovarian carcinoma cells." (PMID 32630699, 2020). "In ovarian cancer, both CCL5 and CCR5 are mainly expressed by CD133+ ovarian carcinoma stem-like cells, which are able to self-renew, induce tumor relapse, and form metastases." (PMID 32630699, 2020). "Only one study demonstrated that downregulated expression of miR-214 in CAFs of ovarian cancer reprogrammed NFs to CAFs, which controlled invasion of cancer cells though stimulating the production and secretion of chemokine CCL5 into the TME." (PMID 30646925, 2019). "Second, cordycepin-mediated Akt inactivation by inhibiting CCL5 reduced nuclear NF-κB preceded SKOV-3 ovarian cancer cell apoptosis." (PMID 29844932, 2018). "Inhibiting CCL5 with a neutralizing antibody was sufficient to reduce tumor growth of co-injected CAFs and ovarian cancer cells in mice." (PMID 30380628, 2018). "As the metastatic tumor grows and depletes the adipocytes in the omentum, the IL-6, CXCL10, and CCL5 secreted by the CAFs induce the ovarian cancer cells to start utilizing glycogen." (PMID 30380628, 2018). "In the present study, we showed that the CCL5-mediated Akt/NF-κB signaling pathway was involved in human ovarian cancer cells after cordycepin treatment." (PMID 29844932, 2018).
ovarian carcinoma (continued). "In this study, we used inflammatory mediator, TNF-α, which has been shown to participate in both the initiation and progression of cancer, and demonstrated that CCL5 is highly expressed in an ovarian cancer cell line under these conditions." (PMID 29844932, 2018). "CCL5 was a target of miR-214 and miR-31, and was responsible for homing of the ovarian cancer cells onto plugs of CAFs in vitro." (PMID 30380628, 2018). "For example, TAM-derived CCL5 was reported to promote macrophages’ capacity for tumour repair and renewal in human epithelial ovarian cancer." (PMID 29342940, 2018). "We then investigated the functional mechanisms underlying the stimulation of the NF-κB signaling pathway by CCL5 in ovarian cancer cells." (PMID 29844932, 2018). "In ovarian cancer, CAFs promote tumor invasion and growth through the secretion of a number of chemokines, cytokines, and growth factors like CCL5, IL-6, IL-8, HB-EGF, and TGF-α, among others." (PMID 30380628, 2018). "Next, we investigated the effect of Akt on NF-κB through cordycepin-regulated CCL5 in ovarian cancer cells." (PMID 29844932, 2018). "In ovarian cancer models, CCL5 has also been shown to be produced by CD133‐positive stem‐like cancer cells." (PMID 28599100, 2017). "In ovarian carcinoma, CCL5 is produced by ovarian cancer stem‐like cells, where it induces EMT in non‐cancer stem‐like cells." (PMID 28599100, 2017). "In ovarian cancer, downregulation of miR-214 in CAFs leads to increase chemokine CCL5 production and secretion into tumor microenvironment." (PMID 26152796, 2015). "To investigate this, we collected cancer tissues, corresponding metastatic tissues, and paracancerous tissues from 20 patients with epithelial ovarian cancer and determined the expression levels of CCL5 and its receptors (CCR1, CCR3, and CCR5)." (PMID 25788271, 2015). "To further validate this observation, we added an anti-CCL5 antibody to CSLC-NCSLC co-cultures derived from the A2780 cell line or from three primary human ovarian cancer tissues." (PMID 25788271, 2015). "CCL5 expression is detected not only in malignant ovarian biopsies, but also in normal biopsies, with minimal expression in ovarian cancer cell lines." (PMID 24523569, 2014). "In ovarian cancer, PARPi activated stromal fibroblasts, which in turn increased CCL5 secretion." (PMID 39201718, 2024). "In BRCA1/2-deficient models in breast and ovarian cancer, PARPi increased cytosolic DNA and activated cGAS-STING (cyclic GMP-AMP synthase-stimulator of interferon genes) signalling, and upregulated pro-inflammatory chemokines such as CCL5 and CXCL10." (PMID 39201718, 2024). "There are also some reports regarding the potential roles of CCL2 and CCL5 in ovarian cancer." (PMID 36766725, 2023). "Furthermore, increased production of CC chemokine ligand 2 (CCL2) and CCL5 by macrophages elevated ovarian cancer-mesothelial cell adhesion." (PMID 36766725, 2023). "In addition to affecting differentiation, TME-derived chemokines can recruit MDSCs to infiltrate into the tumor microenvironment, such as CCL2, CCL5, and other chemokines secreted by breast, gastric, and ovarian cancers." (PMID 37801479, 2023). "CCL5 (RANTES) has already been shown to be a marker of significance in ovarian cancer." (PMID 38032111, 2023). "Ovarian cancer cells treated with CCL5 showed decreased apoptosis when exposed to cisplatin, which was consistent with the finding that platinum-resistant patient samples expressed elevated CCL5 levels compared to platinum-sensitive samples." (PMID 34201616, 2021). "It has been reported that CCL5-induced invasion of ovarian cancer stem-like cells is mediated by CCR1 and CCR3, and CCR3, along with CCR2 and CCR5, are associated with CCL11-stimulated proliferation, migration, and invasion of ovarian cancer cells." (PMID 34206004, 2021).
ovarian carcinoma (continued). "In addition, CCL2 and CCL5 have been detected by cytokine array in the supernatant of stromal cells promoting the resistant phonotype of ovarian cancer cell lines." (PMID 31990955, 2020). "Cisplatin, by inducing the secretion of CCL5 by CAFs, decreases its activity in ovarian cancer." (PMID 32630699, 2020). "CCL5 induced ovarian carcinoma cell drug resistance by activating pSTAT3 and PI3K/pAKT pathways." (PMID 32630699, 2020). "Mechanistically, LL-37 stimulates MSCs to secrete larger amounts of inflammatory and pro-angiogenic factors, such as IL-1 receptor antagonist, IL-6, IL-10, CCL5, VEGF, and MMP-2, and this phenomenon is closely associated with the promotion of ovarian cancer progression and metastasis." (PMID 30568223, 2019). "Therefore, we investigated the effect of Akt on NF-κB through cordycepin-regulated CCL5 in ovarian cancer cells." (PMID 29844932, 2018). "Similarly, the evolving ovarian cancer metastatic tumors are metabolically reprogrammed by CAFs through the secretion of C-C Motif Chemokine Ligand 5 (CCL5), C-X-C motif chemokine ligand 10 (CXCL10), and IL-6 to utilize glycogen." (PMID 30380628, 2018). "Moreover, miR-214 in CAFs was reported to be downregulated in patients with ovarian cancer and in addition, the expression of the pro-tumorgenetic chemokine CCL5 was enhanced, finally promoting the invasion and growth of ovarian cancer cells." (PMID 30443251, 2018). "Next, we focused on determining RANTES/CCL5 expression in ovarian cancer in response to dsRNA." (PMID 30613350, 2018). "CCL5 and CCR5 expressions are also associated with ovarian cancer metastasis." (PMID 28599100, 2017). "However, the clinical relevance of CCL5 to ovarian cancer progression, particularly metastasis, remains to be determined." (PMID 25788271, 2015). "Furthermore, ovarian cancer cells have been shown to reprogram normal fibroblasts into becoming CAFs through the downregulation of miR-214, which increased the production of CCL5 and endowed fibroblasts with tumor-promoting properties." (PMID 25483835, 2015). "Given the relative percentages of these cell types, one could argue that CAFs may play a more important role than CSCs or MSCs in CCL5-mediated ovarian cancer metastasis." (PMID 25788271, 2015). "Therefore, the main source of CCL5 in the tumor, and the relative contribution of the various cell types to CCL5-mediated ovarian cancer metastasis are likely dependent on each individual patient's status." (PMID 25788271, 2015). "Therefore, it is reasonable to conclude that at least in this experimental setting, CCL5 and/or CCL5 expressing CSCs promote ovarian cancer EMT and potential metastasis." (PMID 26328269, 2015). "Taken together, our results redefine the metastatic potential of non-stem cancer cells and provide evidence that targeting the CCL5:CCR1/3/5-NF-κB pathway could be an effective strategy to prevent ovarian cancer metastasis." (PMID 25788271, 2015). "These clinical analyses suggest that the CCL5 signaling is involved in ovarian cancer metastasis." (PMID 25788271, 2015). "In addition, it has been reported recently that CCL5 is one of the most highly upregulated chemokines when CAFs are reprogrammed in epithelial ovarian cancer." (PMID 25788271, 2015). "However, at present several outstanding questions remain and the roles played by CCL5 and its receptors in ovarian cancer are far from being resolved." (PMID 24523569, 2014). "Anti-CCL5 antibodies block the effect of CAFs on tumor growth and cell migration and CCL5-transfected normal fibroblasts increase the invasion of ovarian cancer cells, suggesting that CCL5 is a candidate effector molecule in CAFs, contributing to tumor cell recruitment and growth." (PMID 24523569, 2014). "Additionally, CCL5 supports the aggressiveness of ovarian cancer by attracting regulatory T cells." (PMID 40076892, 2025).
ovarian carcinoma (continued). "Furthermore, high expression levels of CXCL9 and CCL5 were associated with an increased number of tumor-infiltrating CD8+ T cells and better outcomes after PD-1 inhibition in not only patients with ovarian cancer, but also those with other cancers, including colon, lung, and breast cancer." (PMID 37046033, 2023). "Some of these pro-inflammatory molecules including CCL2/MCP-1, CCL5/RANTES and IL-8 are activated during cyclical ovulation; thus, the incessant ovulation theory suggests that inflammation along with other physiological conditions enhances the progression of ovarian cancer." (PMID 30914056, 2019). "Ovarian cancer chemokine landscape profiling revealed chemokines such as CCL2, CCL4, CCL5, CXCL10, and CXCL12 as potential candidates in ovarian cancer." (PMID 41424784, 2025). "In a cultured cell line derived from the ascites of a patient with platinum resistant ovarian cancer (ET2), elevated levels of CCL2, CCL3, CCL4, CCL5, CXCL1, CXCL8 and CXCL10 were detected in the cultured media." (PMID 41424784, 2025). "In ovarian cancer, OCSCs can activate NF-κB and STAT3 signaling through autocrine secretion of CCL5, which promotes their differentiation into endothelial-like cells." (PMID 41373619, 2025). "In this study, we demonstrated that CCL2 and CCL5 derived from macrophages induced mesothelial expression of the adhesion-related genes ITGA2 and VEGFC to increase the adhesion of ovarian cancer cells." (PMID 36766725, 2023). "Together, these data suggest that CCR3 in human ovarian cancer cells can be stimulated by CCL7 from TAMs, as well as CCL5 and CCL11, and can play a critical role in ovarian cancer metastasis." (PMID 34206004, 2021). "Autocrine CCL5 signaling, by activating NF-kB and STAT3, induces ovarian carcinoma stem-like cells to differentiate into endothelial cells and enhances angiogenesis." (PMID 32630699, 2020). "CCL5 mediates invasiveness by activating NF-kB and increasing the secretion of MMP-9, both up-regulated in ovarian carcinoma stem-like cells and also in primary tumors." (PMID 32630699, 2020). "In ovarian cancer, cisplatin induces CAF-derived CCL5 secretion, promoting drug resistance, mediated by PI3K and STAT3 signaling pathway regulation, inhibiting apoptosis and promoting proliferation." (PMID 32499779, 2020). "Specific examples include CCL5 and CCL25 and their cognate receptors CCR5 and CCR9 in breast and ovarian cancers, respectively." (PMID 29358632, 2018). "Meanwhile, a recent study has illustrated that CAF-derived chemokine, namely CCL5, promotes cisplatin resistance by the regulation of PI3K/Akt signalling pathway in ovarian cancer cells." (PMID 28258248, 2017). "CCL5, along with CCL3 and CCL4, is present in ascitic fluids of ovarian carcinoma patients, and their levels positively correlate with the extent of T lymphocytes infiltration." (PMID 24523569, 2014). "CCL5 levels are higher in ovarian cancer patients than in patients diagnosed with benign ovarian cysts and elevated in stages III-IV of ovarian cancer compared to stages I-II." (PMID 24523569, 2014). "In ovarian cancer, the invasiveness of CD133(+) CSCs is enhanced by the chemokine CCL5, which activates CCR3 and CCR5 expressed by the cells to increase matrix metalloproteinase (MMP) 9 secretion." (PMID 25110692, 2014). "Taken together, these data indicated that CCL2 and CCL5 secreted by macrophages can increase the expression of adhesion-related genes ITGA2 and VEGFC via the JNK and Akt pathways in Met5A cells, resulting in enhanced ovarian cancer-mesothelial cell adhesion." (PMID 36766725, 2023). "Higher concentrations of CCL5 are also observed in patients with residual tumor mass than without it, confirming that CCL5 plays a role in ovarian carcinoma progression and suggesting that serum CCL5 levels are a potential diagnostic and prognostic marker." (PMID 32630699, 2020). "Ascites of ovarian carcinoma contains CCL3, CCL4, and CCL5 at levels higher than in patient plasma." (PMID 32630699, 2020).